BRCA1 (BRCA1 DNA repair associated)
Diseases named in the same sentence as BRCA1 in open-access papers (continued):
Sharing a sentence is not in itself a finding about the gene and the disease.
ovarian carcinoma (continued). "The majority of this benefit was in the BRCA1/BRCA2 wild-type (or unknown) group, perhaps demonstrating that combinations can overcome monotherapy dependencies but also highlighting that there is still a lot to learn about biomarkers for anti-angiogenic and PARP inhibitor agents in ovarian cancer." (PMID 26557500, 2015). "In addition, an ovarian cancer susceptibility locus 17q11.2 identified through population-based data has been shown to display a consistent association in BRCA2 carriers, whereas an association of similar magnitude has been ruled out in BRCA1 carriers." (PMID 25919761, 2014). "In addition to BRCA1, the shRNA screen identified the DNA repair genes ATR and XRCC2 as specific genetic hits in CCNE1-amplified cell lines, suggesting that inhibition of the DDR may be a therapeutic strategy in CCNE1-amplified ovarian cancer." (PMID 24624361, 2014). "Besides the use of the MLPA, or other multiplex approaches, to test the effect of genetic variants predicted to affect splicing at the RNA level, it would be useful to test for BRCA1 and BRCA2 mutation negative patients with strong breast and/or ovarian cancer history." (PMID 22350158, 2012). "Interestingly, we recently found that activated form of MAP kinase (ERK) was decreased in BRCA1-suppressed ovarian carcinoma cells (data not shown), and this may be consistent with that activated ERK is reported to work as anti-apoptotic signal." (PMID 19690636, 2007). "They compared 79 patients with PV within the OCCR among 162 BRCA1 PV patients with 83 patients with BRCA1 PV within the non-OCCR and found that patients with PV within the ovarian cancer cluster region (OCCR) had worse PFS (p = 0.038)." (PMID 40427158, 2025). "A recent meta-analysis of BRCA1 promoter methylation showed no survival differences between BRCA1-methylated and non-BRCA-methylated ovarian cancer." (PMID 40869932, 2025). "The promoter hypermethylation of tumor suppressors, BRCA1 and RASSF1A, was significantly higher in ovarian cancers compared to non-neoplastic tissues." (PMID 40563561, 2025). "Additionally, in Belo Horizonte, several mutations in BRCA1 (c.68_69delAG, c.5266dupC, c.181T > G, c.4034delA, c.5123 C > A) and BRCA2 (c.5946delT, c.8537_8538delAG, 4936_4939delGAAA) were assessed in women with ovarian cancer; none of the germline mutations were observed." (PMID 38641594, 2024). "Our results revealed a significant negative correlation between the endogenous levels of miR-155-5p and mRNA BRCA1 within WBC for patients with breast and ovarian cancer and BRCA1-methylation carriers, which is not the case in controls." (PMID 37240365, 2023). "Inclusion of poly (ADP-ribose) polymerase inhibitors (PARPi) as standard therapy for non-mucinous high-grade epithelial ovarian cancer (EOC) led to mainstream, reflex germline and tumour BRCA1/2 testing." (PMID 36765687, 2023). "The National Comprehensive Cancer Network (NCCN), American Society of Clinical Oncology (ASCO) as well as others, recommend germline BRCA1 and BRCA2 genetic testing for all epithelial ovarian cancer patients irrespective of histology." (PMID 37076566, 2023). "Although BRCA1 and BRCA2 work well for breast and ovarian cancers, they do not seem to be reliable for prostate cancer." (PMID 37444562, 2023). "PN3 is a compound heterozygote with breast/ovarian cancers before age 50, but no congenital anomalies – a phenotype more consistent with HBOC (BRCA1) than FA." (PMID 38146508, 2023). "Interestingly, the splice site variant in BRCA1 gene (ENST00000471181.2: c.4357+1G>A) was identified in three related cases, all had a family history of colon, stomach, thyroid and pancreatic cancer without the presence of breast or ovarian cancer in the family." (PMID 36428697, 2022). "Studies conducted by Tsibulak showed higher BRCA1 and BRCA2 mRNA expression in ovarian cancer tissues compared with non-cancerous tissue." (PMID 35807169, 2022).
ovarian carcinoma (continued). "Risk management of further cancers was not described in the three published reports of BRCA1 mosaicism or the report of BRCA2 mosaicism in ovarian cancer." (PMID 36068545, 2022). "This can only indicate that BRCA1/2 genetic testing should be considered for TNBC and HGSC patients even with the absence of hereditary breast and ovarian cancer selection criteria." (PMID 35986351, 2022). "A family history of ovarian cancer was only seen in BRCA1/2 families but not in PALB2 families, where 28.3% of BRCA1 carriers and 12.3% of BRCA2 carriers had a family history of ovarian cancer (p-value = 0.001 and 0.018, respectively)." (PMID 34439348, 2021). "For female index patients with familial breast and/or ovarian cancer, CNV detection should not be restricted to BRCA1/2 due to the relevant proportion of CNVs in further cancer predisposition genes." (PMID 33401422, 2021). "Other mutations, namely c.19_47del, c.668dupA, c.915T>A, c.2418dupA, c.2433delC, c.5030_5033delCTAA in BRCA1 and c.249delG, c.632-1G>A in BRCA2 do not overlap with previously reported breast or ovarian cancer cluster regions." (PMID 34490083, 2021). "In a recent work, absence of LOH was observed in 7% of BRCA1 and 16% of BRCA2 ovarian tumors and was correlated with decreased overall survival in ovarian cancers treated with platinum chemotherapy." (PMID 32850417, 2020). "The level of BRCA1/2 expression was reported to be downregulated by the PI3K inhibitor, BKM120, in wild-type PIK3CA ovarian cancer cells (OVCA433, OVCAR-5, and OVCAR-8), without the involvement of ERK activation." (PMID 32194423, 2020). "AZD compounds did not change the mRNA expression of BRCA1/BRCA in ovarian cancer cells, but AZD8835 inhibited BRCA1/BRCA2 mRNA expression and p-ERK protein expression in OVCAR-8 cells with the KRAS mutation." (PMID 32194423, 2020). "The striking sensitivity of tumors lacking BRCA1 and BRCA2 is exploited in the treatment of breast and ovarian cancers with PARPi." (PMID 31632280, 2019). "Only one study reported BRCA1 among ovarian cancer and no studies reported BRCA2 among ovarian cancer patients, so heterogeneity was not assessed." (PMID 30898109, 2019). "Promoter hypermethylation of tumor suppressors BRCA1 and RASSF1A was significantly higher in ovarian cancers compared to non-neoplastic tissues." (PMID 30646939, 2019). "Sequencing of BRCA1 and BRCA2 genes from tumors of 50 Mexican patients with ovarian cancer was made in a retrospective, non-randomized, and exploratory study." (PMID 29997359, 2018). "While BRCA1 and CCDC98 are downregulated in ovarian cancer, RAP80, MERIT40 and BRCC45 are slightly amplified in ovarian cancer, but not comparable to USP13 amplification." (PMID 28569838, 2017). "The majority of BRCA1 (18/18) and BRCA2 (19/22) carriers were identified from the patients without family history of breast or ovarian cancer." (PMID 27257965, 2016). "A deletion affecting BRCA1, NBR1, and NBR2 at 17q21.31 was identified in a patient with hormone receptor-negative BC with a family history of ovarian cancer (family 252)." (PMID 23967248, 2013). "Second, of women who had a family history of breast and/or ovarian cancer, 42.1% of women with TNBC were BRCA1 or BRCA2 carriers compared with 14.2% of those with non-TNBC (P = < 0.0001)." (PMID 23116406, 2012). "We found that the enhanced phosphor-STAT1 was neither observed in the wild type normal ovarian epithelial HOSE-E6E7 cells, nor in the wild type ovarian cancer cells (OVCA429), but only found in BRCA1-mutant cell lines (HOSE-642, HOSE-636, and UWB1)." (PMID 20576130, 2010). "Activated STAT1 phosphorylation was further confirmed in two additional BRCA1-mutant HOSE cell lines, but not shown in wild type HOSE-E6E7 and ovarian cancer (OVCA429) cells." (PMID 20576130, 2010). "Alteration in methylation of the promoters of BRCA1, MLH1, and FANCF do not seem to commonly mediate clinical chemoresistance in women with ovarian carcinomas." (PMID 19602291, 2009).
ovarian carcinoma (continued). "A deleterious mutation was detected in 20 out of 77 healthy, unaffected probands (26%; 15 in BRCA1 and 5 in the BRCA2 gene) with a severe family history of breast and/or ovarian cancer but no living affected relative." (PMID 18489799, 2008). "Moreover, many other elements of care that are tumour-group-specific are absent from the QIs extracted; for example, BRCA1 and BRCA2 genetic testing to guide treatment decisions in ovarian cancer as per the Society of Gynaecologic Oncology." (PMID 37924649, 2023). "However, the expression of the tumor suppressors BRCA1 and BRCA2 were not significantly altered in ovarian cancer." (PMID 36305848, 2023). "Here, we investigated a radioiodinated PARP inhibitor, [125I]KX1, and show drug target specific DNA damage and subsequent killing of BRCA1 and non-BRCA mutant ovarian cancer cells at sub-pharmacological concentrations several orders of magnitude lower than traditional PARP inhibitors." (PMID 33352773, 2020). "As a first step in resolving the missing heritability of ovarian carcinoma, we present WES data from a large cohort of women diagnosed with HGSOC, who were tested through a familial cancer clinic but returned negative findings for the BRCA1 and BRCA2 genes." (PMID 32242007, 2020). "PIN1 knockdown suppressed LYN Y397 phosphorylation in COV 362 cells (BRCA1 mutant ovarian carcinoma) and PEO-1 and PEO-4 cells (BRCA2 mutant ovarian carcinoma), but not in KURAMOCHI cells (BRCA2 mutant ovarian carcinoma)." (PMID 30590041, 2018). "However, because of the limited number of non-serous cases of ovarian carcinoma subtypes in this study, further study with more cases is needed to clarify the roles of DBC1 and BRCA1 in various histologic subtypes of ovarian carcinomas." (PMID 25823848, 2015). "Of the women with low familial risk of breast and ovarian cancer (diagnosed 36 to 50 with no family history of breast or ovarian cancer], 6.4% and 1.7% of women with TNBC and non-TNBC were found to be BRCA1 carriers, respectively, whereas 2.1% and 5.0% were BRCA2 carriers." (PMID 23116406, 2012). "However, two non-cancerous BRCA1-mutant ovarian epithelial cells (HOSE-642 and HOSE-636) along with BRCA1-mutant ovarian cancer cells (UWB1) revealed a slight and significant increases in cell proliferation at 1, 10 and 100 nM PAF (p < 0.05)." (PMID 20576130, 2010). "Notably, we identified no change in BRCA1 and MGMT mRNA levels in the ovarian cancer patients." (PMID 38542081, 2024). "In ovarian cancer OVCA433 cells, the interruption of Aur A did not alter the expression of Aur B, but the knockdown of Aur B enhanced the expression of Aur A. The silencing of Aur A or/and Aur B promoted the expressions of BRCA1 and BRCA2, compared with in scrambled shRNA-treated control cells." (PMID 24775809, 2014). "Furthermore, in ovarian cancer cell lines, WRAP53β was rapidly recruited to DNA double-strand breaks, where it orchestrated the recruitment of repair factors involved in homologous recombination and non-homologous end joining, including RNF168, 53BP1, BRCA1 and RAD51." (PMID 26426684, 2015).
prostate carcinoma (548 papers, 1998 to 2026). A carcinoma that arises from epithelial cells of the prostate gland. "Some studies suggested that BRCA1 pathogenic variants tend to be associated with aggressive prostate cancer (OR = 1.2–2.0); however, the lower carrier frequency of BRCA1 (0.2%) compared with BRCA2 (1.1%) limits the statistical power." (PMID 41423785, 2026). "These patients were diagnosed at a younger age than either what is expected from the general population or patients with BRCA1-associated prostate cancer in this study." (PMID 41970070, 2026). "Pathogenic alterations in BRCA1/2 (collectively referred as BRCA) occur in up 5%–10% of prostate cancers (PCA), particularly in the metastatic castration‐resistance setting (mCRPC)." (PMID 41538264, 2026). "Inactivating BRCA1/2 mutations confer sensitivity to poly(ADP‐ribose) polymerase inhibitors (PARPi) in prostate cancer (PCA)." (PMID 41538264, 2026). "Clinically, PARPis have demonstrated significant benefit in BRCA1/2-mutated breast, ovarian, pancreatic, and prostate cancers." (PMID 42274517, 2026). "We described a case of aggressive prostate cancer with a BRCA1 pathogenic variant (p.Met1411Thr registered as likely pathogenic in ClinVar) who was treated with multidisciplinary therapy and survived for a long time." (PMID 41423785, 2026). "Here, we reanalyzed the impact of BRCA1 pathogenic variants on aggressiveness using 11 300 prostate cancer patients, adjusting for age and area." (PMID 41423785, 2026). "Other prostate cancer-associated somatic mutations were consistent in some PDOs and parental tumours, such as BRCA1, ALK, STED2, TET2, TRPM8, AURKA, ERBB2, GATA2." (PMID 41403018, 2025). "A study by The Prostate Cancer Transatlantic Consortium (CaPTC) utilizing whole exome sequencing to determine genetic variants in Nigerian patients with advanced prostate cancer identified high frequencies of mutations in the BRCA1, BRCA2, APC, and ATM genes." (PMID 40313245, 2025). "The SIR of prostate cancer was 7.8 (95CI: 5.3‒11, P < 0.001), 5.5 (95CI: 2.9‒9.4, P < 0.001), and 11 (95CI: 6.6‒17, P < 0.001) for men, men with an LP/P BRCA1 variant, and men with an LP/P BRCA2 variant, respectively." (PMID 39838196, 2025). "The novel approach to systematic BRCA1/2 mutation testing represents a paradigm shift in prostate cancer management." (PMID 40427202, 2025). "This marked a significant advance in targeted therapy for prostate cancer patients, particularly those with BRCA1/2 mutations, expanding the clinically available therapeutic options and improving clinical outcomes in these patients." (PMID 40427202, 2025). "Our study revealed that prostate cancer samples stored for a short time had a markedly greater success rate in detecting BRCA1/2 mutation compared with samples stored long-term." (PMID 40427202, 2025). "We also observed the genes associated with DNA repair and aggressive prostate cancer risk (BRCA1 and BRCA2)." (PMID 41463218, 2025). "BRCA1/2 mutations are associated with aggressive prostate cancer phenotypes, overall poorer survival, and early onset of disease; however, data is less robust for other DNA repair genes." (PMID 40832411, 2025). "Germline BRCA2 pathogenic variants (PVs) are known to cause ~4% of prostate cancer, but other homologous repair genes, BRCA1, ATM, PALB2 and Lynch syndrome genes are also involved." (PMID 40046829, 2025). "Denmark had no guidelines for early detection of cancer in men with LP/P BRCA1/2 variants until consensus guidelines for early detection of prostate cancer were implemented in 2023." (PMID 39838196, 2025). "Men with pathogenic BRCA1/2 variants are at higher risk of prostate cancer We included men with likely pathogenic/pathogenic (LP/P) variants in BRCA1/2 in a prostate-specific antigen (PSA) screening program after cascade germline testing since 2014." (PMID 39838196, 2025).
prostate carcinoma (continued). "Carriers of germline BRCA1/2 mutations harbor a significantly elevated risk of developing breast, ovarian, pancreatic, and prostate cancers." (PMID 40830526, 2025). "Early-phase clinical studies—including MEDIOLA, TOPACIO, and KEYLYNK-007—have confirmed the feasibility and safety of combining PARP inhibitors with immune checkpoint blockade, particularly in BRCA1/2-mutated breast, ovarian, and prostate cancers." (PMID 41373427, 2025). "Prostate cancer is considered genetically driven owing to evidence of high heritability, and LP/P BRCA1/2 variants have been of specific interest." (PMID 39838196, 2025). "In the largest pan-cancer analysis of BRCA1/2 alterations published to date (including 7186 prostate cancers), it was shown that germline mutations were present in 35% of patients with BRCA1-altered mCRPC compared with 50% of patients with BRCA2 altered mCRPC." (PMID 39333696, 2025). "Men can be referred for genetic counseling based on familial LP/P BRCA1/2 variants, fulfilled criteria for genetic screening of familial breast and/or ovarian cancer, high-grade prostate cancer before the age of 50, or a family history of prostate cancer." (PMID 39838196, 2025). "To this aim, we conducted a series of analyses assessing ADAR1 expression and activity in patient-derived samples of TNBC and prostate cancer – two of the cancer types in which BRCA1/2 mutations are the most prevalent." (PMID 40730818, 2025). "FANCA deficiency has been shown to sensitize ovarian and prostate cancers to PARPis, demonstrating the existence of synthetic lethality of FA proteins other than BRCA1/2 with PARPi treatment." (PMID 40038300, 2025). "Prostate cancer patients who had BRCA1 pathogenic variant carriers were suggested to be at higher risk for aggressive prostate cancer." (PMID 41463218, 2025). "People with germline likely pathogenic/pathogenic (LP/P) BRCA1/2 variants are at an increased risk of various cancers, including breast, ovarian, pancreatic, and prostate cancers." (PMID 39838196, 2025). "BRCA1 Mutation: Individuals with a BRCA1 mutation have an approximately 3.75-fold higher risk of developing prostate cancer." (PMID 41541272, 2025). "This is consistent with previous studies suggesting that BRCA1‐mutated prostate cancers are associated with more aggressive disease." (PMID 41200281, 2025). "As the first FDA-approved anti-cancer drug that exploits the concept of synthetic lethality, PARP inhibitors (PARPi) are widely employed to treat breast, ovarian, pancreatic, and prostate cancer patients associated with BRCA1 and BRCA2 mutations." (PMID 40299557, 2025). "This study evaluated the sequencing success rate (SSR) of BRCA1/2 mutations using NGS platforms on FFPE samples from prostate cancer patients stored for various durations and correlated success with the DNA fragmentation rate." (PMID 40427202, 2025). "The etiology of prostate cancer remains incompletely understood, but established risk factors include advancing age, race and ethnicity, genetic mutations (such as BRCA1 and BRCA2), Lynch syndrome, and a family history of prostate cancer." (PMID 40493591, 2025). "Germline mutation carriers of BRCA1/2 show defect in homologous recombination (HR) repair and have an increased risk of developing breast, ovarian, pancreatic, or prostate cancers." (PMID 40437549, 2025). "Several exons in the BRCA1 gene, including exons, 2, 13, 17, 20, and 22, have been associated with the prostate cancer progression." (PMID 40725150, 2025). "The use of PARPis in prostate cancer relies on the detection of mutations in several homologous recombination genes in addition to BRCA1 and BRCA2." (PMID 38612902, 2024). "Today, PARP-inhibitors are currently used for the treatment of prostate cancer patients with germinal or somatic mutations in BRCA1 and BRCA2 genes, which results in therapeutically resistant cancers." (PMID 39335746, 2024).